TNF (tumor necrosis factor)
Diseases named in the same sentence as TNF in open-access papers (continued):
Sharing a sentence is not in itself a finding about the gene and the disease.
prostate tumors (15 papers, 2016 to 2025). "We have detected the enrichment of macrophages in PTEN-deficient prostate tumors, and extrapolating to use of co-culture models, we have demonstrated the relevance of macrophages and TNF-α signaling in contributing to the radio-resistance of CaP cells." (PMID 26799286, 2016). "Justified by the enrichment of CD68-positive macrophages detected by IHC in PTEN-deficient prostate tumors, we assessed how exposure to IR modulated TNF-α secretion from THP-1 cells." (PMID 26799286, 2016). "Microarray-based gene expression analysis of larger sample sizes has shown increased expression of proinflammatory cytokines, including IFN-γ, TNF-α and interleukins (IL-1β, IL-6, and IL-8) in prostate tumor tissues of AA men than CAs14,22." (PMID 37698493, 2023). "We found that ADT, by inducing paracrine TNF signaling, disrupts the tumor vasculature in prostate tumors." (PMID 36551505, 2022). "Immunohistochemistry analysis in mice prostate tumors showed that shBAT1 significantly increased TNF-α and IL-6 expression when compared to control and BAT1cDNA tumors." (PMID 36505884, 2022). "Taken together, these data were consistent with TNF mediating the vascular structural damage induced by castration in prostate tumors." (PMID 36551505, 2022). "This work describes studies that, for the first time, functionally define TNF as the mediator of castration-induced vascular damage in prostate tumors." (PMID 36551505, 2022). "The prostate tumors of AA men showed a unique signature of pro-inflammatory cytokines, interferon-alpha (IFNα), IFNγ, tumor necrosis factor-alpha (TNFα), and Interleukin 4 and Interleukin 13 signaling that was associated with metastases and poor prognosis." (PMID 34071280, 2021). "IHC analysis showed that shBAT1 mice prostate tumors increased TNF-α, IL-6, and MMP-10 expression." (PMID 36505884, 2022). "However, we found that ARID1A loss did not reduce Cxcl9 and Cxcl10 expression in PCa cells treated with IFN-γ or TNF-α and mouse prostate tumors." (PMID 36435834, 2022). "On the other hand, it is well known that different doses of TNF induce different effects on prostate tumors, reinforcing the hypothesis that FAM3B may inhibit different mechanisms and types of cell death in DU145 cells, including autophagy and necrosis as suggested." (PMID 29357840, 2018). "In order to overcome this issue, we hypothesize that a Lf-bearing DAB dendrimer complexed to plasmid DNA encoding TNFα, TRAIL, and IL-12 would enhance the delivery of therapeutic DNA to prostate tumors and increase its therapeutic efficacy in vitro as well as in vivo." (PMID 29493296, 2018). "The results show that MSCs treated with TNF-α and IFN-γ promote the yielding of serum VEGF and PDGF and accelerate growth of RM-1 prostate tumors in vivo." (PMID 29268703, 2017). "Another prior study has shown that TNF-α directly and/or indirectly induces proteases such as MT1-MMP and MMP9, and also promotes CCR7 upregulation, thereby contributing to cancer cell migration from breast and prostate tumors." (PMID 33816268, 2021). "The cellular activity of cIAP1 and cIAP2 inhibitors was evaluated through experiments where cytotoxicity of a human prostate tumor cell line (PC-3) was assessed in the presence or absence of cytokines TNF and LT-α." (PMID 27617834, 2016). "Indeed, treatment with IFNγ alone or combined IFNγ and TNFα, but not TNFα alone, sensitized PTPN2- or STUB1-null prostate tumour cells to growth inhibition via measuring the ATP level produced by viable cells." (PMID 35982220, 2022).
Psoriasiform dermatitis (15 papers, 2016 to 2026). A skin abnormality characterized by redness and irritation, with thick, red skin that displays flaky, silver-white patches (scales). "Presumably, the inhibition of TNFα causes increased interferon α expression and homing of Th1 cells to the skin, resulting in psoriasiform dermatitis." (PMID 40481366, 2025). "We report an unusual presentation of TNF-alpha inhibitor-associated psoriasiform dermatitis presenting initially in the nares, specifically the nasal vestibule and mucosa." (PMID 39403182, 2024). "This case demonstrates that paradoxical psoriasiform dermatitis associated with anti-TNF use may involve the nasal mucosa and is a reminder to broaden the differential diagnosis when considering nasal mucosal lesions." (PMID 39403182, 2024). "Interestingly, high IL6 and TNF expression were often associated with psoriasiform dermatitis." (PMID 27050272, 2016). "In the majority of cases, the psoriasiform dermatitis resolved with discontinuation of the anti-TNFαs, changing treatment to a non-TNF inhibitor biologic therapy, or symptomatic treatment with topical corticosteroids." (PMID 39403182, 2024). "A remarkable characteristic anti-TNF-α induced overlap syndrome termed ‘psoriasiform eczema’ or ‘psoriasiform dermatitis’ should be emphasized as it represents the most common skin eruption." (PMID 33802483, 2021). "Helpful clues in light microscopic diagnosis of TNF-α-induced psoriasiform dermatitis are at least 3 dermal eosinophils per histologic section, the presence of plasma cells, neutrophils in the epidermis (subcorneal), and absence of parakeratosis." (PMID 33802483, 2021). "Topical genistein ameliorated the murine IMQ-induced psoriasiform dermatitis with the reduction of skin score, epidermal thickness, and of IL-1β, IL-6, TNF-α, CCL2, IL-17, and IL-23 expression in the skin lesions." (PMID 32751360, 2020). "Resolvin D1 alleviated the IMQ-induced psoriasiform dermatitis and reduced the expression of IL-23, IL-17A, IL-17F, IL-22, and TNF-α in the lesions." (PMID 32751360, 2020). "Biopsy revealed psoriasiform dermatitis, consistent with a diagnosis of anti-TNF-α-induced psoriasiform dermatitis." (PMID 27738572, 2016). "One theory suggests that anti-TNF-α agents cause psoriasiform dermatitis due to attenuated TNF-α-dependent negative feedback on plasmacytoid dendritic cells, resulting in an overproduction of type I interferons." (PMID 39469389, 2024). "Indeed, mast cells were previously demonstrated to play a critical role in the first stages of psoriasiform dermatitis in promoting keratinocyte proliferation and recruiting immune cells through secretion among others of IL6, and TNF." (PMID 27050272, 2016).
pulmonary sarcoidosis (15 papers, 2011 to 2025). Sarcoidosis affecting the lung parenchyma. "Etanercept, a biologic TNF inhibitor has undergone a Phase II clinical trial in pulmonary sarcoidosis patients, however the trial was terminated prematurely due to a high frequency of adverse events." (PMID 37334374, 2023). "Due to the largely inadequate efficacy and unreliable safety profiles of TNF inhibitors, several groups are currently conducting research on alternative approaches to biologic-mediated pulmonary sarcoidosis treatment." (PMID 37334374, 2023). "The binding of bacterial lipopolysaccharide (LPS) mediates the LPS-induced inflammatory response and affects TNF secretion by monocytes, which are involved in excessive cytokine responses and induce the development of pulmonary sarcoidosis." (PMID 35860586, 2022). "Several recent observational studies have described the use and efficacy of anti-TNF agents in extra-pulmonary sarcoidosis in the organ systems." (PMID 32782876, 2020). "Value of TNF-alpha antagonists has been suggested only in a phase II randomised controlled trial (RCT) in pulmonary sarcoidosis." (PMID 27846819, 2016). "Serum TNF-α levels in pulmonary sarcoidosis patients were significantly increased compared with control subjects, but no increase was observed in patients with EPS." (PMID 25866481, 2015). "In addition, BAL levels of TNF-α and IL-6 are significantly higher in pulmonary sarcoidosis patients compared with control subjects." (PMID 25866481, 2015). "This may also explain the differences in TNF-α expression observed between pulmonary sarcoidosis and EPS." (PMID 25866481, 2015). "Thus, in current study we aimed to investigate whether patients with pulmonary sarcoidosis differ from those with EPS in routinely assessed clinical and laboratory data including HLA-DRB polymorphisms, FLC and TNF-α and IL-8 expression." (PMID 25866481, 2015). "The levels of TNF-α and IL-8 in pulmonary sarcoidosis patients were higher than in EPS (P < 0.05) whereas the levels of FLC subunits in EPS were higher than in pulmonary sarcoidosis." (PMID 25866481, 2015). "Third, we showed that gene expression of cytokines such as TNF and IL-17 was upregulated in patients with pulmonary sarcoidosis, but we did not confirm that by measuring interleukin levels in PBMCs or lung tissue." (PMID 35141260, 2022). "We further demonstrated increased levels of serum TNF-α and IL-8 in pulmonary sarcoidosis patients, while TNF-α was not increased in EPS subjects." (PMID 25866481, 2015). "In addition, serum levels of TNF-α were increased in patients with pulmonary sarcoidosis but not in those with EPS." (PMID 25866481, 2015).
radiation pneumonitis (15 papers, 2008 to 2025). Inflammation of the lung due to harmful effects of ionizing or non-ionizing radiation. "In addition, EC UCHL1 has also been reported to attenuate the activity of TNF-α, an inflammatory cytokine that has itself been implicated as a key mediator of radiation pneumonitis." (PMID 37830619, 2023). "Of note, TNF is a key factor that initiates an inflammatory response in vivo and has been shown to play a critical role in early radiation pneumonia." (PMID 35360660, 2022). "Clinical research showed that interleukin (Il)-1, Il-6, tumor necrosis factor (TNF)-α, transforming growth factor (TGF)-β and platelet-derived growth factor (PDGF) are associated with the occurrence of radiation pneumonitis." (PMID 32722546, 2020). "TNF-α is considered the most relevant factor associated with the development of radiation-induced pulmonary fibrosis, and TNF-α plays a critical role in the occurrence and development of radiation pneumonitis." (PMID 27342837, 2016). "Previous studies have also suggested that pro-inflammatory and pro-fibrotic cytokines such as TGF-β and TNF-α, vascular injury, cellular adhesion molecules and oxidative stress are all vital in the development of radiation fibrosis." (PMID 23407465, 2013). "Early release of tumor necrosis factor-alpha (TNF-α) during radiotherapy of thoracic cancers plays an important role in radiation pneumonitis, whose inhibition may provide lung radioprotection." (PMID 28548957, 2017). "in RILI treatment were mainly enriched in cancer pathways, TNF signaling pathways, PI3K-Akt signaling pathways, and HIF-1 signaling pathways, similar to previous reports in radiation pneumonia." (PMID 35360660, 2022). "Through KEGG analysis, the mechanism of RSM treatment of radiation pneumonia may be through PI3K-Akt, HIF-1, TNF signaling pathways." (PMID 34395252, 2021). "The aim of the present study was to investigate the prognostic value of TNF-α, IL-1β, IL-6 and TGF-β1 plasma levels to predict radiation pneumonitis and to evaluate the impact of tumour-derived cytokine production on circulating plasma levels in patients irradiated for NSCLC." (PMID 18682839, 2008).
rectal cancer (15 papers, 2012 to 2026). A primary or metastatic malignant neoplasm that affects the rectum. "GO enrichment was performed on most altered 200 TSSs between rectal cancer patients and healthy donors, and GO terms associated with cancer, including histone modification, DNA repair, DNA modification, and tumor necrosis factor production, were enriched." (PMID 34926480, 2021). "Our results suggested that TNF-α -308 A allele was significantly associated with distant tumor metastasis in rectal cancer patients." (PMID 28575042, 2017). "Furthermore, we analyzed the impact of nRCT on the percentage of rectal cancer-associated slanMo locally producing inducible nitric oxide synthase (iNOS) or tumor necrosis factor (TNF)-α, which play an important role in regulating tumor growth." (PMID 30984181, 2019). "Notably, rectal cancer (a subtype of CRC) patients with TNF-α -308 A allele had a very high risk of distant tumor metastasis [odds ratio (OR) = 4.481; 95% confidence interval (CI): 2.072–9.693; P = 0.00025]." (PMID 28575042, 2017). "The association between TNF-α -308 A allele and distant tumor metastasis remained even significant after adjusting all clinical characteristics (OR = 7.099; 95% CI: 2.482–20.301; P = 0.000256) in rectal cancer patients." (PMID 28575042, 2017). "We found a significant correlation between PD-L1 on DCs treated with TCM from mock-irradiated rectal cancer tissue and TNF-α levels in the supernatants of DCs treated with TCM from mock-irradiated rectal cancer tissue (r = 0.8333, p = 0.01)." (PMID 33540635, 2021). "While iNOS+ slanMo were present in 9 out of 10 post-nRCT rectal cancer tissues, TNF-α+ slanMo were detectable in 7 out of 10 tumor tissues obtained after treatment at varying percentages." (PMID 30984181, 2019). "Here, we determined the impact of nRCT on the percentage of iNOS- or TNF-α-expressing slanMo in matched pre-nRCT and post-nRCT rectal cancer specimens." (PMID 30984181, 2019). "However, nRCT significantly augmented the proportion of infiltrating slanMo locally expressing iNOS- or TNF-α in rectal cancer." (PMID 30984181, 2019). "In addition, nRCT significantly increased the percentage of slanMo locally expressing TNF-α in rectal cancer tissues." (PMID 30984181, 2019). "Taken together, we found that nRCT significantly increases the percentage of rectal cancer-infiltrating slanMo locally expressing iNOS and TNF-α, which can either mediate tumor-promoting or antitumor effects and may affect the efficacy of nRCT in rectal cancer patients." (PMID 30984181, 2019). "Meanwhile, the correlation between TNF-α -308 A polymorphism and distant metastasis remained in rectal cancer patients, indicating that TNF-α -308 G>A polymorphism may be an important risk factor affecting rectal-cancer patients." (PMID 28575042, 2017). "In this context, radio(chemo)therapy has been shown to significantly enhance the proportion of rectal cancer-infiltrating CD8+ T cells and the percentage of tumor necrosis factor α (TNFα) producing monocytes." (PMID 38609887, 2024). "In contrast, iNOS+ slanMo were only found in 2 out of 10 pre-nRCT rectal cancer tissues, while TNF-α+ slanMo were absent in these tissues." (PMID 30984181, 2019). "Generally, in Han Chinese of southwestern China, TNF-α -308 G>A polymorphism may not predispose to CRC risk, but it may significantly increase risk of distant metastasis in rectal cancer patients." (PMID 28575042, 2017).
rhabdomyosarcoma (15 papers, 2008 to 2025). A rare aggressive malignant mesenchymal neoplasm arising from skeletal muscle. "Our present study indicated that APN deficiency conferred a higher frequency of CD8+IFN-γ+ T cells in the spleen and lymph nodes, as well as higher levels of IFN-γ, perforin, and TNF-α and lower levels of IL-10 in the serum of rhabdomyosarcoma-bearing mice." (PMID 35530361, 2022). "Subsequently, we determined the protein levels of IFN-γ, perforin, TNF-α, and IL-10 in the serum of both rhabdomyosarcoma-bearing wild-type and APN−/− mice." (PMID 35530361, 2022). "It showed that baicalin (50 μg/mL) decreased the expression of the FasL protein, a member of the tumor necrosis factor (TNF) family, and caspase-3, a marker of apoptosis, in an in vitro model of the infection in human embryonic rhabdomyosarcoma (RD) cells." (PMID 36145370, 2022). "It was shown that TRAIL in combination with DOX or 4-hydroxy-IFO had highly toxic and pro-apoptotic effects in the TNF-α-sensitive rhabdomyosarcoma cell line KYM-1." (PMID 33321722, 2020). "In the rhabdomyosarcoma cell line KYM-1 exposure to TNF-α induces dose dependent apoptosis via a pro-apoptotic caspase activation and in parallel it triggers the nuclear factor κB (NF-κB)-mediated survival pathways." (PMID 24626175, 2014). "Similar results were obtained using the human rhabdomyosarcoma cell line Kym-1, which endogenously expresses both TNF receptors and is highly sensitive to TNF-induced cytotoxicity." (PMID 22110694, 2011). "We next asked whether the emergent property is specific to cytokine or cell type and found that strongly TNF-responsive KYM-1 rhabdomyosarcoma cells that express FP-RelA28,29 show similarly enhanced responses to TNF pulse trains." (PMID 40781077, 2025). "The results of immunofluorescence and Western blotting showed that Quercetin significantly reduced the expression levels of VP1, TNF-α, and IL-1β in EV71-infected human rhabdomyosarcoma cells." (PMID 37795035, 2023). "As expected, compared to wild-type mice with rhabdomyosarcoma, the serum levels of IFN-γ, perforin and TNF-α of rhabdomyosarcoma-bearing APN−/− mice were much higher, whereas the level of IL-10 in serum was much lower." (PMID 35530361, 2022). "In rhabdomyosarcoma, IGF2BP bound to cIAP1 mRNA directly and promoted the 5′UTR IRES-mediated translation of cIAP1, resulting in resistance to TNFα-mediated cell death." (PMID 34203267, 2021).
rhinitis (15 papers, 2010 to 2024). An inflammation of the mucous membrane lining the nose, usually associated with nasal discharge. "iNOS is a major producer of NO and plays vital roles in patients with inflammatory diseases, including AD, rhinitis, and pollinosis, when it is stimulated by bacterial lipopolysaccharides or various cytokines, such as IL-1β, IL-2, and TNF-α." (PMID 29088069, 2017). "Results of interest include: total effective rate; total nasal symptom score; rhinitis quality-of-life questionnaire; visual analog scale; laboratory test indicators: IgE, IL6, IL10, or TNF-α levels; recurrence rate; adverse events." (PMID 33761721, 2021). "The outcomes of interest include: total effective rate; the total nasal symptom score; Rhinitis quality of life questionnaire (RQLQ); Visual Analog Scale (VAS); Laboratory inspection indicators: the level of IgE, IL6, IL10 or TNF-α; Recurrence rate; adverse events." (PMID 33546014, 2021).
systemic vasculitis (15 papers, 2007 to 2024). "Anti-TNFα drugs have been linked to systemic vasculitis, although renal involvement was rare." (PMID 24558628, 2013). "This case underscores the need for vigilance in patients with RA who develop new symptoms suggestive of systemic vasculitis, especially when on TNF inhibitors like adalimumab." (PMID 39583403, 2024). "As HSP is the most common systemic vasculitis, overproduction of pro-inflammatory cytokines such as TNF-a, IL-6, and IL-8 may be involved in the disease pathogenesis." (PMID 34277463, 2021). "Our report, as few cases in literature, supports a role of anti-TNF therapy in rare systemic vasculitis and, indirectly, it gives evidence that increased levels of TNF-alpha may play a critical role in the inflammatory process associated with PAN." (PMID 24917817, 2014). "The authors concluded that biologic therapy may be helpful in treating primary systemic vasculitis and recommend children with PAN who fail standard therapy or have high cumulative cyclophosphamide dose be treated with rituximab or anti-TNF therapy." (PMID 22046510, 2010).